SIRT1 (sirtuin 1)
Diseases named in the same sentence as SIRT1 in open-access papers (continued):
Sharing a sentence is not in itself a finding about the gene and the disease.
Obesity (continued). "Likewise, the Sirtuin 1 gene, which slows aging and controls appetite, also played an important role in the development of obesity and the disturbance of glucose and lipid metabolism." (PMID 39483856, 2024). "This axis along with SIRT1 correlates with tumor parameters and could have clinical utility in obesity-related CRC prognosis." (PMID 38704452, 2024). "We evaluated circulating SIRT1 levels in relation to fat levels in 32 lipodystrophic patients affected by congenital or acquired LDs compared to non-LD subjects (24 with anorexia nervosa, 22 normal weight, and 24 with obesity)." (PMID 38732001, 2024). "Therefore, GC attenuated obesity‐related muscle wasting by improving mitochondrial function and biogenesis through the activation of SIRT1/PGC1α in the skeletal muscle of mice." (PMID 39055231, 2024). "We found decreased (P < 0.05) mRNA levels of SIRT1 in both groups of individuals with obesity." (PMID 39707172, 2024). "Interestingly, SIRT1 protein content in Kiss1 neurons mirrored these profiles in the models of subnutrition (with increased SIRT1 levels) and obesity (with decreased SIRT1 content)." (PMID 39290326, 2024). "Furthermore, our study aimed to examine the influence of GC on obesity‐induced mitochondrial dysfunction by assessing the activation of SIRT1/PGC1α in the skeletal muscle of mice." (PMID 39055231, 2024). "SIRT1 serum reduction was shown in Alzheimer’s disease and mild cognitive impairment, obesity and lung diseases, suggesting that serum SIRT1 may be a potential biomarker for various aging-associated diseases." (PMID 38529393, 2024). "Furthermore, USP22 reduces hepatic steatosis and obesity by stabilizing Sirt1 protein and regulating Sirt1-dependent mitochondrial respiration." (PMID 38322269, 2024). "In addition, we observed a higher SIRT1 mRNA and protein expression in the overweight/obesity group when we considered the BMI classification only, which is the opposite of what we expected since miR-34a targets SIRT1 mRNA directly." (PMID 38662716, 2024). "However, there is a paucity of literature about the clinical relevance of the MEG3/miR-27a/IGF1 and MEG3/miR-181a/SIRT1 co-expression networks in predicting obesity-related CRC." (PMID 38704452, 2024). "Notably, resveratrol, one of the well-known bioactive polyphenols and popular exercise mimetic, protects against obesity-induced impairments in mitochondrial biogenesis by stimulating SIRT1/AMPK/PGC1α pathway." (PMID 38976215, 2024). "Low concentrations of SIRT1 have been found in obesity in both serum and tissue." (PMID 38732001, 2024). "Interestingly, serum SIRT1 levels were found to be reduced in obesity and increased in anorexia nervosa (AN) and in patients experiencing weight loss." (PMID 38732001, 2024). "Additionally, GME treatment activated the hepatic AMP-activated protein kinase and Sirtuin 1, which showed anti-obesity effects." (PMID 39415841, 2024). "This is complementary to the relevant research results that quercetin exerts anti-inflammatory effects by activating AMPK and the downstream protein molecule SIRT1 in LPS-induced macrophage inflammation, obesity-induced inflammation, diabetes-induced inflammation, and other inflammatory responses." (PMID 37959807, 2023). "Furthermore, SRT1720 is a specific SIRT1 activator that prevents diet-induced obesity and insulin resistance through enhancing fatty acid oxidation in the liver, muscle, and brown adipose tissue in mice." (PMID 37834101, 2023). "In adipose cells, SIRT1 acts as an inhibitor of adipogenesis, and also plays a major role in regulating the expression and secretion of adiponectin, an anti-inflammatory hormone that is decreased in obesity and type 2 diabetes." (PMID 37862340, 2023). "The miR-221/SIRT1 pathway may be a potential therapeutic target for reducing adipocyte inflammation during obesity." (PMID 37537674, 2023). "Upon obesity, SIRT1 is known to be repressed both in mice and humans." (PMID 38026693, 2023).
Obesity (continued). "However, PGC-1α activity and mitochondrial biogenesis are stimulated by miR-149 and HFD and obesity have been demonstrated to drastically diminish SIRT1 activity by reducing the expression of miR-14948." (PMID 37726284, 2023). "Small molecules that activate JMJD3 or promote the interaction of JMJD3 with SIRT1 specifically decreased the lipid levels, which may provide a therapeutic approach to treat obesity and hepatosteatosis." (PMID 37834101, 2023). "In both obesity and ageing, the decrease in the production of sirtuin 1 may involve the NF-κB pathway." (PMID 38276294, 2023). "Epigenetic modifications, particularly histone acetylation-deacetylation and its related enzymes, such as sirtuin 1 (SIRT1) deacetylase, may have substantial roles in the pathogenesis of obesity and its associated health issues." (PMID 37862340, 2023). "Furthermore, hypothalamic SIRT-1 over-expression can control food intake and BW gain through increased leptin sensitivity in obesity." (PMID 36991247, 2023). "Resveratrol is reported to exert its anti-obesity effect by the browning of WAT as well as by targeting several intracellular components such as sirtuin-1 (SIRT-1), adenosine monophosphate-activated protein kinase (AMPK), and the peroxisome proliferator-activated receptor coactivator-1 (PGC-1)." (PMID 37251328, 2023). "The significant positive correlation between histone acetylation levels and insulin resistance indices suggests that long-term induction of insulin resistance in obesity and in cases with low SIRT1 expression might be mediated by hyperacetylation of histones." (PMID 37862340, 2023). "Authors suggested that early targeting of SIRT1 may represent a crucial strategy to prevent age- and obesity-related microvascular dysfunction." (PMID 38304233, 2023). "We also examined the expression of the SIRT1 gene and found it to be significantly lower in individuals with obesity compared with normal-weight children, as well as those with insulin resistance and MetS, compared with the children with obesity who did not present with insulin resistance or MetS." (PMID 37862340, 2023). "Furthermore, it has shown anti-diabetic and anti-obesity effects by increasing phosphorylated Sirtuin 1 (SIRT1) in the liver and muscle and AMPKα in the muscle." (PMID 37110159, 2023). "SIRT1 overexpression effectively reduces obesity and insulin resistance in NAFLD rodents." (PMID 37894893, 2023). "The increase in SIRT1 induced by KD may represent an adipose tissue protective mechanism against inflammation, obesity, and insulin-resistance induced by a high-fat diet." (PMID 36555502, 2022). "The effect of FCLL-GABA against SIRT1 decay may have important implications, considering the critical role of SIRT1 in obesity." (PMID 35458241, 2022). "Sirtuin type 1 (Sirt1) is classified as a class III HDAC and is known to be involved in the extension of lifespan in mammals and other organisms and in protection against age-associated diseases (such as diabetes and obesity)." (PMID 35733777, 2022). "The AMPK/SIRT1/PGC1α pathway is inhibited in the skeletal muscles of humans and mice with obesity." (PMID 35565942, 2022). "Previous investigations indicated the decreased SIRT1 expression in the eWAT in obesity." (PMID 35458241, 2022). "Besides, Pacs-2 knockout mice have elevated liver sirtuin 1 (SIRT1) activity and are protected from diet-induced obesity." (PMID 36138342, 2022). "Sirt1 is also involved in energy balance by regulating glucose homeostasis and fat metabolism, similar to AMPK, making it an additional target for the development of therapies for metabolic diseases caused by obesity." (PMID 36010531, 2022). "We already explained in the previous section, and based on literature findings, that an increase in miR-204 in obesity could lead to downregulation of SIRT1 and BDNF and, therefore, to a decrease in the SNA." (PMID 35155042, 2022).
Obesity (continued). "SIRT1 dysregulation in adipose tissue disturbs autophagic activity to degrade lipid molecules, leading to lipid droplets accumulation in the adipocytes and contributing to the development of obesity." (PMID 35909524, 2022). "Studies suggest that dysregulation of SIRT1-mediated autophagy may participate in the development of obesity, T2DM, diabetic cardiomyopathy, and hepatic steatosis." (PMID 35909524, 2022). "Our findings suggest that Sirt1 activation may be a viable therapeutic strategy to combat arterial stiffening in the face of obesity/high fat diet consumption." (PMID 35561022, 2022). "As increases in aortic stiffness are an independent risk factor for CVD, our data suggests that interventions to increase Sirt1 activation may be efficacious to reduce arterial stiffening in obesity." (PMID 35561022, 2022). "Still, regarding the cardioprotective effect of geniposide, Ma and colleagues (2018) also demonstrated that treatment with geniposide increased SIRT1 protein levels and, consequently, its activity in the heart, which were decreased in a model of obesity induced by feeding mice with a high-fat diet." (PMID 35883477, 2022). "SIRT1 tends to reduce fat storage and protects adipose tissue from obesity-induced inflammation; it controls fatty acid metabolism and increases oxidative metabolism in the liver; and it improves glucose tolerance by regulating insulin synthesis in the pancreas." (PMID 35207605, 2022). "It is speculated that DHM can promote adipocyte brown-resistance to obesity through the AMPK-PGC1α-SIRT1 pathway." (PMID 35252293, 2022). "In conclusion, CR may ameliorate obesity and associated metabolic disorders by activating the AMPK/SIRT1/PGC-1α energy-sensing network and mitochondria-mediated thermogenesis." (PMID 35721807, 2022). "However, the inhibition of sirtuin 1 in some neurons augmented sensitivity to diet-induced obesity on account of decreasing energy expenditure." (PMID 35873818, 2022). "Herein, we aim to provide a review of the literature focusing on the epigenetic mechanisms of KBs and SIRT1 involved in metabolic outcomes, seeking to describe a direct link between these molecules during the ketogenic dietary management of obesity and its complications." (PMID 35956321, 2022). "Stimulating the acupoints CV12 and ST40 may influence SIRT1 in the hypothalamic arcuate nucleus, inducing an anorectic effect and reducing obesity with IR." (PMID 35903320, 2022). "Interestingly, SIRT1 reduces VAT deposition in animal models of obesity, and fat cell hypertrophy occurs when SIRT1 mRNA expression is low." (PMID 36555502, 2022). "Accumulating evidence demonstrated that SIRT1 could prevent cartilage degeneration by activating autophagy, and suppress adipogenesis to ameliorate obesity." (PMID 35922815, 2022). "AMPK activation is associated to SIRT1 activation controlling many metabolic functions, including differentiation of cultured adipocytes, and it has been extensively associated to the promotion of browning in HFD-induced obesity." (PMID 36142372, 2022). "Indeed, many of the protein superfamilies modulated by resveratrol are relevant for obesity and metabolic diseases, including SIRT1 and proteins related to nitric oxide (NO), insulin, and nuclear hormone receptors (such as PPARγ)." (PMID 35889827, 2022). "AMPK activation is associated to SIRT1 function in the control of key metabolic functions, including differentiation of cultured adipocytes, and it has been extensively associated with the promotion of browning in HFD-induced obesity." (PMID 36142372, 2022). "Activation of SIRT1 by the activator resveratrol or overexpression of SIRT1 can be beneficial for the treatment of metabolic and neurodegenerative diseases such as type 2 diabetes, obesity, Alzheimer’s disease, and Parkinson’s disease." (PMID 34017061, 2021). "we were interested in whether the protection role of exenatide is related to the SIRT1 changes in the kidney in obesity." (PMID 34434166, 2021).
Obesity (continued). "A decrease of SIRT7 expression was also observed during obesity in humans, thus, further research is required to elucidate whether or not a difference exists across organisms in the cross-talk between SIRT1 and SIRT7." (PMID 33806509, 2021). "The reduced function or presence of SIRT1 in HFD-fed mice or during obesity may be explained by the observation that HFD induces cleavage of SIRT1 proteins." (PMID 33806509, 2021). "Several in vitro studies have demonstrated that resveratrol has an anti-obesity effect by negatively regulating white adipogenesis via inhibiting PPARγ and C/EBPα, activating Sirtuin 1 (SIRT1) and (PPARγ Coactivator 1) PGC1α, attenuating white adipogenesis and lipid accumulation." (PMID 34371900, 2021). "Myeloid-specific deletion of SIRT1 enhanced obesity-induced inflammation." (PMID 34099590, 2021). "The expression of SIRT1 has reduced in diabetes milieus, obesity and during aging." (PMID 34434166, 2021). "In addition, SIRT1 can affect biological clock rhythm through stem cell function and inflammation during obesity and neurodegeneration." (PMID 34590471, 2021). "Furthermore, specific activation of Sirt1 by SRT1720 protected mice from diet‐induced obesity and insulin resistance." (PMID 33159388, 2021). "Many co-morbid conditions like diabetes, obesity and hypertension further deteriorate the aging process and different mechanisms rescuing different cells get benefitted by the action of SIRT1." (PMID 32727328, 2021). "In addition, CE attenuated obesity-associated decrement in muscle mitochondrial mass and function, partially by modulating AMPK/SIRT1 pathway." (PMID 34684660, 2021). "SIRT1 is required for the homeostatic defense against diet-induced obesity in mice." (PMID 33806509, 2021). "Thus, the suppression of SIRT1 by obesity leads to metabolic dysfunction, such as hyperlipidemia and hyperglycemia." (PMID 34306160, 2021). "SIRT1 control of circadian rhythm and melatonin may affect cellular glucose tolerance, stem cell function, and inflammation during obesity and neurodegeneration." (PMID 34356626, 2021). "Taken together, IGF2 depletiondownregulated expression levels of PGC1α and SIRT1, increased ROS production andmitochondrial fission, and decreased mitochondrial biogenesis and ATP production, whichcontributed to the development of fatty liver and obesity." (PMID 33988719, 2021). "This compound increases expression of genes associated with lipid metabolism such as SIRT1, FOXO1 and PPARγ and could therefore be considered for the treatment of obesity and metabolic impairment." (PMID 33806509, 2021). "We further hypothesized that FGF19 had protective effects against obesity‐induced muscle atrophy via the AMPK/SIRT‐1/PGC‐1 signalling pathway." (PMID 33751819, 2021). "Indeed, resveratrol, a naturally occurring SIRT1 agonist, was shown to alleviate diet-induced obesity and insulin resistance in mice." (PMID 34578872, 2021). "Overexpression of SIRT1 effectively blunts obesity-induced adipose tissue macrophage infiltration." (PMID 34863096, 2021). "At present, seven mammalian sirtuins (SIRT 1-7) have been identified, with SIRT1 and SIRT6 shown to exert their metabolic actions in the hypothalamus, both with crucial roles in eliciting responses to dampen metabolic complications associated with obesity." (PMID 33572672, 2021). "Similar to diet-induced obesity, hypothalamic SIRT1 protein expression levels also decrease with age, which may contribute to age-associated weight gain." (PMID 32143417, 2020). "Notably, the reduction of SIRT1 promotes adipogenesis of the visceral adipose-derived stem cells (ASC), and patients with obesity exhibit significant lower SIRT1 mRNA expression in visceral ASC compared to subcutaneous ASC." (PMID 33202604, 2020). "Decreased hippocampal SIRT1 expression is noted in the context of obesity/HFD." (PMID 32408716, 2020).
Obesity (continued). "Some studies have shown that single nucleotide polymorphisms (SNPs) in SIRT1 can change its expression and activity, leading to individual susceptibility to obesity and related metabolic disturbances in non-HIV infected subjects." (PMID 32106282, 2020). "Previously, we found that resveratrol administration to the offspring could improve fatty acid metabolism and reduce obesity by activating SIRT1 from retroperitoneal fat tissues." (PMID 32316577, 2020). "The aim of this study is to examine whether maternal or paternal SIRT1 overexpression can ameliorate maternal obesity-induced metabolic consequences in the offspring." (PMID 33027895, 2020). "In addition, SIRT1 protects against diet-induced obesity and inflammation as well as obesity-related metabolic dysfunction." (PMID 32102680, 2020). "HFD-induced obesity may impair memory that is mediated by neuroepigenetic dysregulation of SIRT1 within the hippocampus." (PMID 32408716, 2020). "Collectively, maternal HFD/obesity decreased adiponectin, pAKT, SIRT1, and BDNF in male rat fetal brain and maternal resveratrol treatment could restore adiponectin, pAKT, and BDNF." (PMID 32408716, 2020). "Therefore, CD38 represents an important regulator of SIRT1 activity and SIRT1 functions, including maintenance of cellular bioenergetics, obesity and senescence, mainly because it modulates the availability of NAD+ to the SIRT1 enzyme." (PMID 32423100, 2020). "The hepatoprotective role of this marine polysaccharide also includes a sirtuin, namely sirtuin-1 overexpression, which alleviates obesity and insulin resistance through suppression of hyperglycemia, reducing inflammation and stimulation of enzymatic antioxidant response." (PMID 32380741, 2020). "Collectively, maternal HFD/obesity decreased adiponectin, pAKT, SIRT1, and BDNF in rat placenta." (PMID 32408716, 2020). "Resveratrol, a Sirt1 activator, was shown to prevent high-fat induced obesity in rodents." (PMID 33040052, 2020). "As mentioned in the previous section, NAD+-dependent SIRT1 activity is pivotal for the hypothalamic regulation of energy homeostasis and circadian physiology, which are disrupted during the process of obesity and aging." (PMID 32143417, 2020). "In addition to providing neuroprotection against neurodegenerative diseases, the activation of SIRT1 has been shown to confer protection against cerebral ischemia and metabolic diseases such as obesity and type 2 diabetes." (PMID 33269110, 2020). "In the whole body, BBR may regulate SIRT1 in ATMs by major mechanisms that suppress local and systemic obesity-induced inflammation, subsequently alleviating metabolic dysregulation." (PMID 33390968, 2020). "SIRT1 did not correlate to specific risk factors for endometrial carcinoma suh as diabetes (p = 0.858), obesity (p = 0.983) or hypertension (p = 0.539)." (PMID 32388637, 2020). "Hence, several studies have investigated alterations in the metabolic organ NAD+ levels and SIRT1 activity in rodent models of obesity and aging." (PMID 32143417, 2020). "In contrast, these mutant mice on a high-fat diet (HFD) are vulnerable to diet-induced obesity due to reduced EE, because SIRT1 in POMC neurons is required for the brown adipose tissue-like remodeling of the perigonadal white adipose tissue through sympathetic activation." (PMID 32143417, 2020). "Moreover, NAD(+)-dependent histone deacetylase sirtuin-1 (SIRT1) expression is reduced in obesity, at least in part via iNOS-induced inactivation of SIRT1." (PMID 32971941, 2020). "Supporting this hypothesis, it has been shown that Resveratrol, an activator of SIRT1, was able to alleviate obesity-induced oxidative stress and growth retardation in oocytes." (PMID 33027895, 2020). "This SIRT1 can regulate antioxidant genes and participates in the regulation of certain signaling pathways, such as AMPK activation, associated with metabolic disorders and obesity." (PMID 32013273, 2020).